HIF1A (hypoxia inducible factor 1 subunit alpha)
Diseases named in the same sentence as HIF1A in open-access papers (continued):
Sharing a sentence is not in itself a finding about the gene and the disease.
prostate carcinoma (430 papers, 2006 to 2026). A carcinoma that arises from epithelial cells of the prostate gland. "Hypoxia, a hallmark of solid tumors, is commonly associated with elevated HIF1α expression in prostate cancer tissues." (PMID 40643528, 2025). "Lactylation of HIF-1α enhances KIAA1199 transcription further promoting hypoxia-associated oncogenic pathways in prostate cancer." (PMID 40535811, 2025). "The presence of VM in prostate cancer is associated with higher expression of certain related factors, like HIF1α, EphA2, ZEB1, and Sp1." (PMID 37810976, 2023). "Angiogenin expression has been associated with STAT3 signalling in prostate cancer and with HIF-1α in oral cancer." (PMID 37896150, 2023). "The association of HIF-1α expression with clinicopathological significance has recently been reported in various cancer types, including prostate cancer." (PMID 36139362, 2022). "HIF-1α is overexpressed in various cancers, including prostate cancer, and is associated with increased risk and a poor diagnosis of PCa." (PMID 35740392, 2022). "miR-34a-5p downregulation in prostate cancer is responsible for the overexpression of HIF1A, IGFBP2 and PIK3CB, associated with tumor development and progression." (PMID 35741059, 2022). "Meanwhile, the inhibition of AKT/GSK-3β was also associated with the attenuation of HIF-1α in prostate cancer." (PMID 34026649, 2021). "Loss of IDH2 in prostate cancer cells leads to ROS-dependent stabilization of HIF-1α underwent normoxic conditions, which is essential for increased mitochondrial trafficking and tumor cell movements." (PMID 33637686, 2021). "HIF1α activation and the association with the “Warburg effect” were also demonstrated in prostate cancer cells that receive lipids from marrow adipocytes." (PMID 33706793, 2021). "Stratified analysis indicated that HIF-1α SNPs (rs11549465, rs11549467, or rs2057482) were mainly associated with the risk of pancreatic, lung, head and neck, and prostate cancers." (PMID 33154192, 2020). "It was demonstrated that HIF-1α accumulated in prostate cancer tissues, and HIF-1α overexpression was associated with castration resistance, proneness to recurrence, and metastasis in prostate cancer patients." (PMID 32215176, 2020). "The increasing level of HIF-1α was found in the prostate cancer tissues and was highly correlated with the metastatic risk of prostate cancer." (PMID 32215176, 2020). "Loss of ERβ in prostate cancer induces transcriptional down-regulation of prolyl hydroxylase 2, resulting in decreased HIF1-α hydroxylation, and thereby decreased ubiquitination by the von Hippel-Lindau tumor suppressor and increased HIF1α protein expression." (PMID 33194742, 2020). "Heat shock protein 60 (HSP60) is a novel apoptotic and prostate cancer prognostic marker that is involved in the regulation of HIF-1α protein stability and associated with prostate cancer progression." (PMID 31088536, 2019). "In prostate cancer, we observed an association of increased HIF-1α and LAPTM4B expression with advanced tumor stage and metastasis." (PMID 30746305, 2019). "Recent studies have also implicated them, especially HIF1A, in regulating neuroendocrine phenotype in prostate cancer." (PMID 32039001, 2019). "HIF1α is usually expressed in tumors and has recently been shown to increase the clinical risk of prostate cancer." (PMID 31700698, 2019). "Several studies demonstrated HIF1α-rs11549465 polymorphism contributed to increase the risk of prostate cancer." (PMID 29942264, 2018). "The transporter proteins ABCG2 and MDR1 cause chemotherapy resistance in prostate cancer, where both genes were shown to be increased during hypoxia and are direct targets of HIF-1α." (PMID 30555629, 2018). "In the present study, we incorporated previously published studies to more systematically explore the impact of HIF1A rs11549465 polymorphism on prostate cancer risk." (PMID 28415653, 2017).
prostate carcinoma (continued). "Studies from our laboratory have shown that cancer-associated fibroblasts (CAFs) promote EMT of prostate cancer cells through an ROS-dependent HIF-1α stabilization." (PMID 28352611, 2017). "The use of cytoplasmic rather than nuclear staining, is unlikely to have influenced our results, since this method has been published before, reporting positive associations of HIF-1α with prostate carcinoma and prognosis." (PMID 28143503, 2017). "Experimental studies with prostate cancer cells demonstrated that HIF-1α overexpression was associated with higher proliferation and metastatic potential." (PMID 28143503, 2017). "Hypoxia has been linked with aggressiveness and metastatic progression in prostate cancer and we have shown previously that HIF-1α gene expression is increased in prostate bone tumors from HFD mice as compared to LFD mice." (PMID 27588494, 2016). "Recently, we showed that MSeA blocks growth of rat and human prostate cancer cells 24, an effect that has been associated with downregulation of HIF-1α even under hypoxic conditions." (PMID 24515947, 2014). "Given the high risk of progression to metastases and of development of CRPC and prostate cancer-specific death, the diagnostic accuracy of HIF1α in determining these outcomes was analyzed." (PMID 23342109, 2013). "Over-expression of HIF-1α is implicated in the pathogenesis of many cancers including prostate carcinoma, in which it is associated with advanced clinical stage and chemo-resistance." (PMID 23594994, 2013). "Previous studies have reported the existence of HIF1A P582S and A588T missense polymorphisms in renal, urothelial and prostatic carcinomas, however the effects remain conflicting." (PMID 23723982, 2013). "Two missense polymorphisms, HIF1A P582S and A588T, were most widely studied SNP sites, which were then supposed to modify the risk of urinary cancers, such as renal, urothelial and prostate cancers." (PMID 23723982, 2013). "Further analysis showed that Smad3 overexpression in prostate cancer cells could overcome the decreased HIF-1α and PFKP caused by docetaxel." (PMID 36536346, 2022). "HIF-1α accumulation is associated with hypoxia-induced EMT in prostate cancer cells." (PMID 32215176, 2020). "Above controversies over the role of HIF1A rs11549465 polymorphism in prostate cancer incidence may be due to several reasons." (PMID 28415653, 2017). "In line with our recent data suggesting an autocrine effect of S1P in regulating HIF-1α in hypoxic prostate cancer cells, the silencing of Spns2 was associated with a significant inhibitory effect on HIF-2α accumulation under hypoxia in both CAKI-1 and A498 cells." (PMID 26974204, 2016). "We reasoned that HIF-1α might underlie this differential response of low-AR and high-AR prostate cancer cells due to its interaction with AR to form a ternary complex with β-catenin that is required for hypoxia-activated AR transactivation." (PMID 25821081, 2015). "Therefore, one mechanism for the upregulation of HIF1α by KLF5 loss in PTEN deficient or insufficient prostate cancer cells appears to be the activation of AKT." (PMID 25896712, 2015). "Constitutive over-expression of HIF-1α is observed in many types of cancers including prostate carcinoma, but the mechanisms underlying this event remain largely unknown." (PMID 23594994, 2013). "Moreover, ectopic expression of Smad3 in prostate cancer cells could overcome the decreased HIF-1α expression and its target gene PFKP caused by docetaxel treatment." (PMID 36536346, 2022). "A polymorphism rs11549465 in HIF1A gene has been proposed to be correlated with the occurrence risk of prostate cancer in several studies, but no definitive conclusion on the role of the single nucleotide polymorphism (SNP) in prostate cancer development has been drawn." (PMID 28415653, 2017).
prostate carcinoma (continued). "The current findings suggest that HIF1A P582S polymorphism correlates with urinary cancers risk in Caucasian population, while A588T polymorphism may increase the risk of urinary cancers in Asian population and prostate cancer." (PMID 23723982, 2013). "In the present study, we provide preliminarily genetic evidence that HIF1A P582S polymorphism is a potential factor for the susceptibility of urinary cancers in Caucasian population, while A588T polymorphism contributes to the risk of urinary cancers in Asian population and prostate cancer." (PMID 23723982, 2013). "Acriflavine inhibits HIF-1 dimerization, disrupts the HIF-1α/β interaction, and effectively suppresses autophagy in prostate cancer cells at concentrations of 5–25 μM." (PMID 40004215, 2025). "Previous studies have indicated that HIF-1α physically interacts with ERRα in prostate cancer cells." (PMID 40723264, 2025). "This context-dependent transcriptional partnership reflects the remarkable plasticity of HIF1α in prostate cancer and adds a new dimension to our understanding of how hypoxia remodels lineage transcriptional programs." (PMID 40643528, 2025). "In bone metastasis, accompanied with adipocyte, prostate cancer cells exhibit high glycolytic rates and increased HIF-1α expression, which regulates Warburg effect genes, leading to enhanced lactate production and inhibition of oxidative phosphorylation." (PMID 41179661, 2025). "The SphK1/HIF‐1α signaling cascade has emerged as a central regulator of the anticancer effects of chrysin in hypoxia‐induced PC‐3 prostate cancer cells." (PMID 41427031, 2025). "In prostate cancer, MCT1 mediates an increase in intracellular lactate, which enhances KIAA1199 transcription and promotes angiogenesis in prostate cancer via lactylation of HIF1α." (PMID 40584617, 2025). "Hypoxia-inducible factor 1-alpha (HIF-1α) is a key player in the metabolic adaptation of prostate cancer cells to hypoxic conditions." (PMID 40535811, 2025). "PRKAR2B, which encodes Protein Kinase CAMP-Dependent Type II Regulatory Subunit Beta, is crucial for maintaining the growth of prostate cancer cells by activation of HIF-1α." (PMID 40867253, 2025). "Quantum dots (QDs) have demonstrated the ability to inhibit HIF-1α expression in breast and prostate cancers, thereby promoting autophagic cell death." (PMID 40004215, 2025). "Another study indicates that evodiamine can inhibit prostate cancer growth by reducing lactylation of hypoxia‐inducible factor 1 alpha (HIF1α) in prostate cancer cells, a finding corroborated by animal experiments." (PMID 40443721, 2025). "Altogether, our findings uncover a regulatory axis whereby HIF1α negatively regulates FOXA1 protein stability in prostate cancer cells, thereby suppressing androgen receptor signaling and promoting hypoxia-responsive transcriptional programs." (PMID 40643528, 2025). "To investigate the role of HIF1α in transcriptional reprogramming under hypoxia, we used LNCaP 1F5 prostate cancer cells, which constitutively express high levels of HIF1α." (PMID 40643528, 2025). "A related study has shown that dihydroartemisinin suppresses glycolysis in LNCaP cells by inhibiting the PI3K/AKT pathway and downregulating HIF-1α expression in prostate cancer cells." (PMID 40728997, 2025). "Given prior studies implicating HIF1α in tumor cell motility, we examined its role in prostate cancer migration." (PMID 40643528, 2025). "Previous studies have shown that PI3K and AKT signals are involved in promoting HIF-1α synthesis in prostate cancer cells, and that mTORC1 enhances glycolytic flux by activating HIF-1α transcription and translation." (PMID 41203617, 2025). "These clinical findings align with our cell line data, demonstrating that hypoxia and HIF1α activation promote prostate cancer progression by suppressing AR targets while activating hypoxia-inducible pathways." (PMID 40643528, 2025).
prostate carcinoma (continued). "Another isomer, δ-tocotrienol, showed promising results on prostate cancer stem cells through the down-regulation of HIF-1α and HIF-2α." (PMID 39859345, 2025). "Immunoprecipitation of endogenous HIF1α pulled down FOXA1, while reciprocal immunoprecipitation of FOXA1 confirmed specific co-precipitation of HIF1α, demonstrating bidirectional interaction in prostate cancer cells." (PMID 40643528, 2025). "Inhibition of HIF-1α suppressed prostate cancer, Evodiamine impairs HIF-1α histone lactylation to inhibit Sema3A-mediated angiogenesis and PD-L1 by inducing prostate cancer cell ferroptosis." (PMID 40535811, 2025). "Monocarboxylate transporter protein 4 (MCT4)‐mediated lactate induces HIF1A histone lactylation in advanced prostate cancer (PC) cells, stabilizes HIF1α protein expression in a normoxic environment, enhances PD‐L1 transcription and promotes PC progression." (PMID 39417674, 2024). "Evodiamine significantly reduced the growth of prostate cancer xenografts in nude mice in vivo by suppressing the expressions of HIF-1α, lactylation of histone 3 on lysine residue 18 (H3K18la), GPX4, PD-L1, and proliferation markers." (PMID 39690423, 2024). "In prostate cancer cells, lactate treatment boosted the expressions of hypoxia-inducible factor-1α (HIF-1α) and PD-L1 while concurrently reducing Sema3A expression." (PMID 39690423, 2024). "Dampened activities of chrysin on angiogenesis and the HIF-1α level in DU145 prostatic carcinoma cells is achieved viathe PI3K/Akt pathway." (PMID 38611849, 2024). "Hypoxia increased TRPM7 expression and HIF-1α accumulation in androgen-independent prostate cancer cells." (PMID 38255793, 2024). "Chrysin also disrupted HSP90/HIF-1α binding, reducing HIF-1α stability in DU145 human prostate cancer cells, and modulated HIF-1α expression through the PI3K/Akt pathway." (PMID 39519572, 2024). "For example, quercetin inhibited HIF-1α accumulation and synthesis under hypoxic conditions in several cancer cell lines, including LNCaP prostate cancer cells, SkBr3 breast cancer cells, and CX-1 colon cancer cells." (PMID 39519572, 2024). "In prostate cancer, elevated lactate promotes the lactylation and stability of HIF1α to induce KIAA1199 transcription and KIAA1199-mediated angiogenesis, vasculogenic mimicry and depolymerized hyaluronic acid levels." (PMID 38200523, 2024). "Our results are consistent with the results of a previous study that showed that PTX-induced ROS accumulation stimulates the expression of HIF-1α and activates caspase-3 signaling to promote apoptosis in prostate cancer cells." (PMID 38845972, 2024). "HIF-1α is a major factor involved in the regulation of cellular responses in prostate cancer; it is activated and decreased by hypoxia and targets the HIF pathway." (PMID 38324544, 2024). "The bioinformatics study performed by the GO functional analysis tool provided by the TNM plotter confirmed the increased expression of PIGF in prostate cancers compared to metastasis (p = 5.14 × 10−2) Similar data have been observed for HIF-1α expression." (PMID 39457506, 2024). "HIF-1α has been found to be excessively expressed in various types of tumors, such as ovarian, lung, gastric, breast, pancreatic, and prostate cancer, within a clinical environment." (PMID 38842687, 2024). "IPA also predicted HIF1α (P < 9.43E-06) and EMT (P < 5.63E-06) as key pathways associated with prostate cancer development in AA." (PMID 37476073, 2023). "Subsequently, RIIβ expression was found to be induced under hypoxic conditions and, as HIF-1α is the mediator of the response to hypoxic stress, a positive regulatory feedback loop involving RIIβ and HIF-1α was identified in prostate cancer." (PMID 37830741, 2023). "NPAS2 is upregulated in prostate cancer and promotes cell survival by promoting glycolysis and inhibiting oxidative phosphorylation through HIF-1A signaling in PCa cells." (PMID 36978001, 2023).
prostate carcinoma (continued). "Curcumin inhibits cancer-associated fibroblast-driven prostate cancer invasion, EMT, ROS production, and decreased CXCR4 and IL-6 receptor expression through MAOA/mTOR/HIF-1α signaling." (PMID 38008819, 2023). "Hypoxia-inducible factor (HIF-1α), as a prognostic factor and transcription factor of malignant tumors, is highly expressed in many malignant tumors, as well as in prostate cancer 9,10." (PMID 37781511, 2023). "In prostate cancer, it has been shown that HIF1a protein levels decrease with prolonged exposure to hypoxia." (PMID 38033871, 2023). "They concluded that mechanistically, melatonin inhibits HIF-1α stabilization and nuclear translocation in prostate cancer cells via inactivation of the SPHK-1 and Akt/GSK-3β, culminating in the demonstrated anti-angiogenic activity." (PMID 37191417, 2023). "Recent study reported that propofol regulated the activity of HIF-1α to reduce prostate cancer cells malignancy." (PMID 37383725, 2023). "Evidence in prostate cancer cells suggests that the ERRα/HIF-1α interaction reduces the proteosomal degradation of HIF-1α." (PMID 37175690, 2023). "Other mechanisms of melatonin-induced inhibition of HIF-1α in prostate cancer cells have also been studied." (PMID 37191417, 2023). "We found that BM macrophages engulfing apoptotic prostate cancer cells promoted HIF-1α stability and subsequent HIF-1α and p-STAT3 nuclear translocation to induce the expression of the pro-inflammatory cytokine MIF." (PMID 36496973, 2022). "CAFs enhanced the EMT process by activating the MAOA/mTOR/ HIF1α signaling axis and enhanced the migration and invasion abilities of prostate cancer cells." (PMID 35589690, 2022). "In this study, the SPHK-1/HIF-1α pathway was identified as a potential therapeutic target for aggressive prostate cancer treatment." (PMID 36139362, 2022). "It has been disclosed that ZFP91 boosts prostate cancer propagation via the NF-κB pathway and tumorigenesis of colon cancer by the upregulation of the HIF-1α level 18,29." (PMID 35165513, 2022). "In another study, it was shown that PRKAR2B increases the expression of HIF-1α, which provides a growth advantage in prostate cancer by increasing the Warburg effect." (PMID 36250071, 2022). "PDGF-BB has been shown to upregulate the Bcl-2 family member named Myeloid Cell Leukemia-1 (Mcl-1) by forming a transcription complex between β-catenin and HIF-1α in prostate cancer cells." (PMID 35158804, 2022). "EZN-2968′s potent, selective, and sustained inhibition of HIF-1α mRNA and protein levels and tumor cell growth has been validated in prostate cancer and glioblastoma cell lines." (PMID 36139386, 2022). "Another study showed that hypoxia can simultaneously increase the expression of TRPM7 and induce the accumulation of HIF-1α in androgen-independent prostate cancer cells." (PMID 36033489, 2022). "In PC3 prostate cancer cells, HIF-1α, NF-κB, and COX-2 pathways are activated by CAF-mediated ROS generation, leading to EMT and metastatic dissemination." (PMID 35884382, 2022). "A functional genomics screen study has shown that TNFα-induced ADCK2 expression in human osteosarcoma cells and prostate cancer cells inhibited ROS production, and it was required for HIF-1α stability." (PMID 36439873, 2022). "Hypoxic conditions lead to activation of HIF1A/HIF-1α (hypoxia inducible factor 1 subunit alpha) that subsequently enhances the proliferation and survival of prostate cancer cells." (PMID 35317831, 2022). "Analysis of prostate cancer cases showed that HIF-1α can bind to the HRE of lncRNA FALEC in prostate cancer cells and induce the increase in FALEC expression." (PMID 36139386, 2022). "Hypoxia is a typical feature of prostate cancer, and a relationship between HIF1A-induced microRNA 224 (miR224) and natural cytotoxicity triggering receptor 1 (NCR1) has been uncovered in hypoxic prostate tumors." (PMID 35659268, 2022).